CASS4 (Cas scaffold protein family member 4)
Description:
Docking protein that plays a role in tyrosine kinase-based signaling related to cell adhesion and cell spreading. Regulates PTK2/FAK1 activity, focal adhesion integrity, and cell spreading.
Synonyms: HEPL; C20orf32; HEFL; CAS4
Tractability: Antibody: its Gene Ontology location is reachable by antibodies, with medium confidence.
Gene: Protein-coding gene on chromosome 20 (56,412,049 to 56,460,387, forward strand). Ensembl gene ENSG00000087589.
Subcellular location: Cytoplasm, cytoskeleton; Cell junction, focal adhesion
Gene Ontology:
Molecular function: protein tyrosine kinase binding
Biological process: positive regulation of cell migration; positive regulation of phosphatidylinositol 3-kinase/protein kinase B signal transduction; positive regulation of protein tyrosine kinase activity; positive regulation of substrate adhesion-dependent cell spreading; cell migration; cell surface receptor protein tyrosine kinase signaling pathway
Cellular component: cytoplasm; focal adhesion; plasma membrane; cytoskeleton
Genetic constraint (gnomAD): Loss-of-function variants: 21 observed, 57.06 expected, observed/expected ratio (o/e) 0.37, 90% interval 0.26 to 0.53. The upper end of that interval is the gene's LOEUF score, 0.53, which puts it in group 2 of 6, group 1 being the genes least tolerant of losing a copy. Missense variants: 850 observed, 1,031.8 expected, observed/expected ratio (o/e) 0.82, 90% interval 0.78 to 0.87. Synonymous variants: 409 observed, 411.15 expected, observed/expected ratio (o/e) 0.99, 90% interval 0.92 to 1.08.
Homologues: Orthologues: chimpanzee CASS4 (98% identical), macaque CASS4 (94% identical), pig CASS4 (73% identical), dog CASS4 (73% identical), rabbit CASS4 (66% identical), guinea pig CASS4 (65% identical), rat Cass4 (65% identical), mouse Cass4 (65% identical), tropical clawed frog cass4 (39% identical), zebrafish cass4 (31% identical), Drosophila melanogaster p130CAS (18% identical). Paralogues in human: NEDD9 (26% identical), BCAR1 (25% identical), EFS (14% identical).
Diseases named in the same sentence as CASS4 in open-access papers:
CASS4 is named in the same sentence as 16 diseases in open-access papers, as found by Europe PMC text mining. Sharing a sentence is not in itself a finding about the gene and the disease. The quoted sentences say what the papers report.
Alzheimer disease (6 papers, 2014 to 2025). A progressive, neurodegenerative disease characterized by loss of function and death of nerve cells in several areas of the brain leading to loss of cognitive function such as memory and language. "Cass4 codes for a scaffolding protein that has been implicated in Alzheimer’s disease, possibly through the toxic effects of Tau." (PMID 28367307, 2017). "In Alzheimer’s disease (AD), we analyzed RNA-seq data from the AD Functional Genomics consortium FunGen-xQTL project and identified unproductive splicing events in 18 AD risk genes, including TSPAN14, PICALM, and CASS4, likely mediating genetic effects on disease risk." (PMID 40291686, 2025). "In this article, we first introduce the pathological features of Alzheimer's disease, and describe recent data linking NEDD9, CASS4, and PTK2B to this syndrome." (PMID 25594051, 2014).
Crohn disease (1 paper, 2020). A gastrointestinal disorder characterized by chronic inflammation involving all layers of the intestinal wall, noncaseating granulomas affecting the intestinal wall and regional lymph nodes, and transmural fibrosis. "CASS4 is a well-known candidate gene of AD and has recently been studied in the context of immune system function and the pathogenesis of developmental and autoimmune disorders, including Crohn’s disease, cancer, and other diseases." (PMID 32816243, 2020).
lung carcinoma (1 paper, 2021). "Regarding "Cluster 3" which was elevated in group F, the gene capable to represent the tendency is CASS4 whose overexpression has been associated with promotion of lung cancer invasion by inhibiting E-cadherin expression and activating AKT signaling pathway." (PMID 33691672, 2021).
cancer (8 papers, 2011 to 2023). A tumor composed of atypical neoplastic, often pleomorphic cells that invade other tissues. "We explored the correlation between FCGR1A and CASS4 in various cancer types through TIMER database." (PMID 33344503, 2020). "The LOAD-associated genes, cas scaffolding protein family member 4 (CASS4) and protein tyrosine kinase 2 beta (PTK2B), have been studied primarily for their roles in the directly cancer-relevant processes of migration and survival signaling." (PMID 29723294, 2018). "The Cas scaffolding proteins (NEDD9/HEF1/CAS-L, BCAR1/p130Cas, EFSSIN, and HEPL/CASS4) regulate cell migration, division and survival, and are often deregulated in cancer." (PMID 21765937, 2011). "Similar to our results, low expressions of CASS4 and LSAMP indicated poor prognosis in other types of cancers." (PMID 36506313, 2022). "CASS4 and PTK2B act as interacting partners regulating oncogenesis and metastasis, and are known to be active in the brain during development and in cancer." (PMID 29723294, 2018). "For historical reasons, the bulk of molecular characterizations of NEDD9, CASS4, and PTK2B have stressed their roles in cancer." (PMID 25594051, 2014). "Reciprocally, these functions can better inform our understanding of the action of NEDD9, CASS4 and PTK2B in cancer." (PMID 25594051, 2014). "The described collection of functional relationships for NEDD9, CASS4 and PTK2B in AD is a generalizable approach of thinking about genotypes, phenotypes and ultimately functionality to understand diseases ranging from Alzheimer's to cancer." (PMID 25594051, 2014). "Intriguingly, NEDD9, CASS4, and PTK2B have been much studied as interacting partners regulating oncogenesis and metastasis, and all three are known to be active in the brain during development and in cancer." (PMID 25594051, 2014). "Finally, while the main focus of this review has been on the roles of NEDD9, CASS4, and PTK2B in LOAD, many of the LOAD-relevant processes can further highlight the significance of these proteins in cancer." (PMID 25594051, 2014). "Interestingly, over the past two decades, several studies have identified roles for NEDD9, CASS4, and PTK2B in these processes, but this literature is typically underappreciated in the context of neurodegenerative diseases, in contrast to the focus on this signaling cluster in cancer and metastasis." (PMID 25594051, 2014).
psychiatric disorder (1 paper, 2025). A disorder characterized by behavioral and/or psychological abnormalities, often accompanied by physical symptoms. "Twelve lead SNPs were located within 10 genes (BIN1, TMEM106B, AP001257.1, PICALM, SLC24A4, PVRL2, APOE, CLPTM1, CTB-179K24.3, and CASS4) for AD, and all three stress-related psychiatric disorders were identified using FUMA." (PMID 39975850, 2025).
CASS4 also shares sentences with these, for which no sentence is quoted: infection (4 papers); neoplasia (2); amyloidosis (1); breast carcinoma (1); cognitive decline (1); disorders of the brain (1); meningioma (1); multiple sclerosis (1); neurodegenerative disease (1); neurodevelopmental disorder (1); virus infection (1).